ARIH1 (ariadne RBR E3 ubiquitin protein ligase 1)
Diseases named in the same sentence as ARIH1 in open-access papers (continued):
Sharing a sentence is not in itself a finding about the gene and the disease.
ARIH1 also shares sentences with these, for which no sentence is quoted: prostate carcinoma (3 papers); cutaneous squamous cell carcinoma (1); head and neck squamous cell carcinoma (1); hepatocellular carcinoma (1); infectious disease (1); influenza (1); large cell lung carcinoma (1); plague (1).